PHB1 (prohibitin 1)
Diseases named in the same sentence as PHB1 in open-access papers (continued):
Sharing a sentence is not in itself a finding about the gene and the disease.
tumor (continued). "The results showed that PHB1 silencing significantly promoted the subcutaneous tumour growth of LPLUNC1 over-expression NPC cells." (PMID 30886235, 2019). "Given to NPC is an inflammation-related cancer, LPLUNC1 and PHB1 function in anti-tumour and anti-inflammation, and we demonstrated that LPLUNC1 inhibited NPC growth by suppressing the Stat3 pathway." (PMID 30886235, 2019). "To further investigate the role of neddylation loss on tumor cell metabolism, we examined energetic metabolism using a Seahorse® XF24 Analyzer equipment in hepatocytes isolated from Phb1-KO mice." (PMID 25650664, 2015). "In order to further study neddylation inhibition-induced tumor cell death, we used well-differentiated tumor Phb1-KO hepatocytes." (PMID 25650664, 2015). "In summary, following neddylation inhibition in Phb1-KO mice, a reduced malignant phenotype translating into tumor regression as a consequence of tumor cell death is observed." (PMID 25650664, 2015). "Moreover, DIRAS1 and PHB1 protein levels were positively correlated in tumor samples, with linear regression yielding an R2 of 0.7857 (p = 0.0480)." (PMID 40723377, 2025). "Consequently, for effective tumor treatment, more in‐depth research and precise targeting strategies for PHB1 are essential, given its distinct functional roles in various tumor types, which are influenced by its subcellular localization." (PMID 40285603, 2025). "Moreover, most studies have mainly focused on understanding how PHB1 affects tumours, leaving fewer investigations into the effects of PHB2, especially in GC." (PMID 38200519, 2024). "siRNA inhibiting prohibitin-1 (PHB-1) to promote apoptosis of tumor cells is proved valid." (PMID 37056723, 2023). "In vitro results based on NCI-H460 cells showed that the NPs could silence PHB1 and induce tumor apoptosis effectively." (PMID 34452113, 2021). "In addition, prohibitin 1 (PHB1) plays a tumor-suppressive role and positively regulates MAT1A while suppressing c-Myc." (PMID 32998289, 2020). "In this study, we aimed to investigate the role of PHB1 in NPC and whether the anti-tumour role of LPLUNC1 is dependent on PHB1." (PMID 30886235, 2019). "Considering the function of PHB1 in anti-tumour and anti-inflammation, PHB1 might play an important role in the initiation and progression of NPC." (PMID 30886235, 2019). "IHC analyses revealed the levels of LPLUNC1 and PHB1 in the tumour xenografts." (PMID 30886235, 2019). "Next, we detected the effects of PHB1 silencing on the tumour suppression of LPLUNC1 in vivo." (PMID 30886235, 2019). "Together, our findings revealed a novel mechanism underlying the anticancer effect of LPLUNC1 and clarified that PHB1 may represent a novel, promising candidate tumour suppressor gene in NPC, with potential therapeutic target value." (PMID 30886235, 2019). "Therefore, our study indicates that PHB1 acted as a tumour suppressor gene by inhibiting NF-κB activity." (PMID 30886235, 2019). "PHB1 acted as a tumour suppressor gene by inhibition of NF-κB activity." (PMID 30886235, 2019). "In addition, PHB1 has a strong anti-tumour and anti-inflammatory effect via blocking NF-κB and STAT3 signalling pathway." (PMID 30886235, 2019). "PHB1 was originally described as a tumor suppressor for its ability to inhibit cell proliferation." (PMID 29029444, 2017).
tumor (continued). "We examined whether the tumour suppression of LPLUNC1 requires PHB1 expression." (PMID 30886235, 2019). "As a downstream target of LPLUNC1, we wondered whether PHB1 functions as a tumour suppressor." (PMID 30886235, 2019). "It was found in our previous work that PHB1 upregulated by Long-palate, lung and nasal epithelium clone 1 (LPLUNC1) enhances the anti-tumor effects in nasopharyngeal carcinoma through counteract TRIM21-mediated ubiquitination to inhibit the NF-κB activity." (PMID 36348375, 2022). "High PHB1 tumor expression is connected with poorer overall survival in patients with non-small cell lung cancer (NSCLC), further indicating PHB1 as a therapeutic target." (PMID 34452113, 2021). "We found that SH2D4A and PHB1 co-localize in mitochondria and treatment of tumor cells with the PHB ligand FL3 reduced SH2D4A, STAT3, and PHB1 protein levels but led to increased co-localization of PHB1 and pSTAT3-Ser727." (PMID 33257655, 2020). "PHB1, the principal mammalian PHB, is a potential tumor suppressor due to its antiproliferative action, and therefore named prohibitin." (PMID 33354575, 2020). "We used short-hairpin RNA to knock down the expression of PHB1 in HNE1 and CNE1 cells with LPLUNC1 over-expression and examined the tumour suppressive effects of LPLUNC1." (PMID 30886235, 2019). "Consistent with this, PHB1 and PHB2 were recently shown to be overexpressed in lymphoid and myeloid tumor cell lines compared to normal naive and activated primary human PBMCs." (PMID 31684984, 2019). "Collectively, our findings in vitro and in vivo suggest that PHB1 silencing can attenuate the tumour suppressor function of LPLUNC1 in NPC, indicating that the tumour suppressive role of LPLUNC1 partly requires PHB1 expression in NPC cells." (PMID 30886235, 2019). "The HDAC4 isoform has been described to promote fibrotic liver injury in a prohibitin 1-knockout (Phb1-/-) animal model which also develops HCC, suggesting a possible contribution of S1P to the observed effect in tumor development." (PMID 31861664, 2019). "LPLUNC1 and PHB1 were significantly downregulated in NPC tissues, and the decreased LPLUNC1 and PHB1 expression significantly correlated with a poor prognosis of NPC, which suggests a candidate tumour suppressor role in NPC." (PMID 30886235, 2019). "Densitometric analysis indicated that PHB1 and PHB2 were overexpressed (> 1 fold) in 61% and 79% of tumor samples, respectively compared to normal donor PBMCs." (PMID 29029444, 2017). "Strong positive expression of PHB1 and PHB2 (100%; score 2 or score 3) was observed in the cytoplasm of tumor cells in all NASH HCCs." (PMID 28218651, 2017). "Compared to naive primary human PBMCs, PHB1 and PHB2 protein levels were 4.3 to 18.4 and 3.6 to 18.4 fold higher (p < 0.05) in the tumor cell lines, respectively." (PMID 29029444, 2017). "Taken together, PHB1 and PHB2 proteins are overexpressed in lymphoid and myeloid tumor cell lines compared to normal naïve and activated primary human PBMCs." (PMID 29029444, 2017). "Knockdown of PHB1 prevents cisplatin-induced mitochondrial division and Oma1-mediated cleavage, as well as changes in OPA1 processing, suggesting that mitochondrial dynamics involved in PHBs play an important role in controlling tumor chemoresistance." (PMID 36348375, 2022). "Thus, binding of PHB1 by FL3 led to reduced L-OPA1 levels promoting the alteration of mitochondrial structure and function of tumor cells." (PMID 33257655, 2020). "Thus, in the present study, we determined the clinical relevance of PHB1 and PHB2 in 82 DLBCL tumor samples and show their potential importance in DLBCL cell survival and proliferation." (PMID 31684984, 2019). "The functional role of PHB1 and PHB2 in tumorigenesis and the mechanism involved requires further investigation for potential implication of prohibitin domain family proteins in tumor diagnosis and treatment." (PMID 29784973, 2018).
tumor (continued). "In conclusion, these observations indicate that PHB1 and PHB2 activity contribute to tumor cell survival in the context of mitochondrial protection and therefore strengthen the potential value of these proteins as therapeutic targets in the treatment hematologic cancers." (PMID 29029444, 2017). "Taken together, these findings support the role of PHB1 and PHB2 in hematologic tumor cells for maintenance of mitochondrial integrity, which may facilitate the energy requirements of these tumor cells." (PMID 29029444, 2017). "For example, phosphorylation of PHB1 on Thr258 in the raft domain of the plasma membrane is required for the activation of Ras-induced Raf-MEK-ERK and the PI3 K/Akt pathways, which promote tumor cell proliferation and metastasis." (PMID 26091791, 2015). "Third, Rocaglamide A, a member of the flavagline class of compounds, binds to both PHB1 and PHB2 at the cell membrane to inhibit Raf activation and Raf-MEK-ERK-mediated cell cycle progression and cell proliferation in tumor cell lines, without inducing mitochondrial fragmentation." (PMID 26497683, 2015).
infection (20 papers, 2015 to 2026). The state of being infected such as from the introduction of a foreign agent such as serum, vaccine, antigenic substance or organism. "Verified in this experiment, PA14 infection of C. elegans triggers stress and immune responses, accompanied by upregulated expression levels of phb-1 and phb-2." (PMID 41409596, 2025). "On day 3 post infection, cells were harvested and lysed before incubation with a sepharose slurry of protein G followed by incubating with a goat polyclonal anti-PHB1 antibody, followed by a second round of incubation with protein G sepharose slurry." (PMID 38594317, 2024). "We chose to focus these studies on prohibitin 1 (PHB), as a study of a liver-specific prohibitin 1 knockout showed that prohibitin was protective against infection and inflammation." (PMID 35407523, 2022). "In this study, using contemporary methods such as VOPBA, LC-MS/MS analysis, infection inhibition, surface localization, Co-IP and surface expression, PHB1/2 was identified as a receptor for DENV-3 in SH-SY5Y and CHME-3 cells." (PMID 32306962, 2020). "Infection inhibition and siRNA assays confirmed the role of PHB1/2 in the entry of DENV-3 into SH-SY5Y and CHME-3 cells but not in U-87 MG cells." (PMID 32306962, 2020). "Further, antibodies to PHB1 reduced the infection to 55 and 73% on SH-SY5Y and CHME-3 cells respectively in a dose dependent manner." (PMID 32306962, 2020). "Previous studies showed that the expression of Phb1 not only decreased the inflammatory status but also increased the inflammatory response after infection." (PMID 33175859, 2020). "The role of PHB1/2 was further established by siRNA mediating silencing of PHB1/2 which significantly limited the infection in SH-SY5Y and CHME-3 cells." (PMID 32306962, 2020). "One protein, prohibitin 1 (PHB1) was downregulated by infection with both DENVs." (PMID 38594317, 2024). "In L. donovani, PHB1 is present on the flagellar surface and in the aflagellar pole, and the overexpression of PHB1 increased the amount of protein in the cell membranes, resulting in parasites with greater capability of infection." (PMID 33830991, 2021). "However, after 72 h of infection, the parasitization index (number of amastigotes/cell) was significantly higher (p ≤ 0.05) in cells infected with parasites overexpressing PHB1 or PHB2." (PMID 33830991, 2021). "Located in phospholipid-rich subcellular sites such as the plasma membrane and mitochondrial inner membrane, PHB1 and PHB2 are emerging as important host targets for bacteria and viruses, influencing infection and host responses by these microbes." (PMID 42311502, 2026). "Overexpression of PHB1 increased DENV protein expression, level of infection and genome copy number." (PMID 38594317, 2024). "We present an approach leveraging quartzcrystal microbalance with dissipation monitoring (QCM-D) technologyfor rapid (∼30 min) detection of prohibitin-1 (PHB1), a proteinwith pleiotropic biological function that dramatically increases inblood during the acute phase of an infection." (PMID 41473019, 2025). "In contrast, immunoreactive levels of FOXK2, OPA1, MFF, and PHB1 generally were preserved in the majority of Fbxo24+/− mice regardless of infection." (PMID 38735474, 2024). "On the contrary, no inhibition of infection was noted in SH-SY5Y cells when treated with anti-VIM antibody or in U-87 MG cells when treated with anti-PHB1/2 antibodies." (PMID 32306962, 2020). "Knocking down Phb2 and, to a lesser extent, Phb1 expression in cells that overexpressed Apol9 significantly enhanced but did not fully restore infection." (PMID 26196674, 2015).
metabolic disease (4 papers, 2021 to 2025). A congenital disorder (due to inherited enzyme abnormality) or acquired (due to failure of a metabolically important organ) disorder resulting from an abnormal metabolic process. "In this study, we examined the hepatic transcriptome of liver-specific Phb1 deficient mice and identified biological functions and genes associated with hepatotoxicity, lipid metabolism, and metabolic disorders." (PMID 34539442, 2021). "Dysfunctions of PHB1/PHB2 are known to be associated with podocyte cytotoxicity, oxidative stress, and metabolic diseases." (PMID 40168274, 2025).
adenocarcinoma (3 papers, 2010 to 2017). A common cancer characterized by the presence of malignant glandular cells. "To define the role of PHB1 in HeLa cells, an adenocarcinoma cell line, we generated stable cell lines expressing PHB1-directed shRNAs using the constitutive pLL3.7 lentiviral shRNA expression system." (PMID 20856874, 2010).
neurodegenerative disease (3 papers, 2021 to 2022). A disorder of the central nervous system characterized by gradual and progressive loss of neural tissue and neurologic function. "There is evidence that suggests the drug PDD005, which targets PHB1 and PHB2, can protect against neurodegenerative diseases such as AD and Parkinson’s disease (PD)." (PMID 34868199, 2021). "Nitric oxide has been found to be involved in neuroprotection, but its role in neurodegenerative diseases, as well as how its regulation of PHB1 results in neuroprotection, is not clear." (PMID 34868199, 2021).
hematologic malignancies (1 paper, 2017). "Subsequently, siRNA-mediated knockdown of PHB1 and PHB2 in Kit225 cells significantly enhanced sensitivity to H2O2-induced cell death, suggesting a protective or anti-apoptotic function in hematologic malignancies." (PMID 29029444, 2017).
hematologic tumor (1 paper, 2017). "siRNA mediated knockdown of PHB1 and PHB2 in Kit225 cells significantly enhanced their sensitivity to ROS-induced cell death, suggesting a protective function in human hematologic tumor cells." (PMID 29029444, 2017). "We provide novel evidence that PHB1 and PHB2 are upregulated in hematologic tumor cells to maintain mitochondrial integrity and protect against oxidative stress-induced cell death." (PMID 29029444, 2017). "Identifying the subcellular localization of PHB1 and PHB2 in hematologic tumor cells is important to understanding their function in hematologic cell transformation, as well as the general mechanism of action in normal human lymphocytes." (PMID 29029444, 2017). "Previous reports suggest PHB1 mRNA levels are inversely proportional to cellular proliferation in a number of cell types, however the results presented herein indicate PHB1 and PHB2 are upregulated during the oxidative stress response in hematologic tumor cells." (PMID 29029444, 2017).
neuromuscular disease (1 paper, 2021). "The mitophagy function of the PHB complex (PHB1/2) may have protective effects against aging and neuromuscular diseases." (PMID 33802593, 2021).
peripheral neuropathy (1 paper, 2021). A disorder affecting the peripheral nervous system. "Therefore, Phb1 deletion from SCs causes sensory-motor peripheral neuropathy." (PMID 34078899, 2021). "In line with the typical manifestation of peripheral neuropathy in mice, Phb1-SCKO animals show clenching of hind limbs towards the body when suspended by the tail." (PMID 34078899, 2021). "The rapid, demyelinating peripheral neuropathy observed in Phb1-SCKO mice seems to be significantly more severe than that of previous conditional knockout mice for mitochondrial genes." (PMID 34078899, 2021). "Here, we show that deletion of prohibitin 1 in Schwann cells minimally perturbs development, but later triggers a severe demyelinating peripheral neuropathy." (PMID 34078899, 2021). "This peripheral neuropathy also leads to clear functional impairments in Phb1-SCKO mice." (PMID 34078899, 2021).
PHB1 also shares sentences with these, for which no sentence is quoted: cervical cancer (4 papers); Insulin resistance (4); neuroblastoma (4); Alzheimer disease (3); glioblastoma (3); cognitive decline (2); colon carcinoma (2); diabetic nephropathy (2); diffuse large B-cell lymphoma (2); lung adenocarcinoma (2); lymph node metastasis (2); neuropathy (2); non-alcoholic steatohepatitis (2); papillary thyroid cancer (2); schizophrenia (2); Adult onset (1); age-related hearing loss (1); amyotrophic lateral sclerosis (1); asthenospermia (1); autoimmune pancreatitis (1); breast tumor (1); cardiac hypertrophy (1); cerebral artery occlusion (1); cervical tumors (1); Cognitive impairment (1); colorectal tumors (1); COVID-19 (1); dementia (1); diabetic retinopathy (1); endotoxemia (1).
A further 32 diseases each share a sentence with PHB1 in 1 paper.